CRP (C-reactive protein)
Diseases named in the same sentence as CRP in open-access papers (continued):
Sharing a sentence is not in itself a finding about the gene and the disease.
infection (continued). "C-reactive protein (CRP), an acute phase protein synthesized by the liver in response to infection or inflammation, exhibits rapid elevation shortly after onset and serves as a sensitive marker for tissue damage and inflammation." (PMID 38915920, 2024). "The levels of white blood cell(WBC), CRP, and PCT in the intracranial infection group and the non-infection group were compared." (PMID 39611102, 2024). "Biomarkers for early infection diagnosis, including procalcitonin (PCT), Interleukin-6 (IL-6), and (CRP), have been extensively studied." (PMID 38956649, 2024). "Starting from a baseline mean CRP concentration of 8.8 ± 16.7 mg/L in the VCO group and 11.6 ± 25.4 mg/L in the control group, it can be inferred that the participants had either an infection or inflammation upon admission." (PMID 38282651, 2024). "The following is the results of the assessment of infection-related indicators: white blood cells (WBC) count 19.84 × 109/L, neutrophils 6.5 × 109/L, C-reactive protein (CRP), procalcitonin 1.77 ng/mL and faecal calprotectin > 1800 ug/g." (PMID 38519924, 2024). "It is difficult to diagnose early postoperative infection only relying on serum biomarkers (such as WBC, CRP, and ESR) as they are physiologically increased due to the healing process in the early postoperative stage." (PMID 38660585, 2024). "Some participants thought that CRP could help clinical decision making, such as whether or not to prescribe antibiotics, use additional diagnostic tests, and whether to admit or discharge patients, particularly in those with no clear focus of infection." (PMID 38504318, 2024). "CRP and TNF-α are inflammatory biomarkers that are elevated in response to infection or inflammation." (PMID 39182041, 2024). "Our study confirms the value of combining traditional inflammatory markers such as CRP and PCT with indices such as NLR and MPV to assess the severity of infections in head and neck abscesses." (PMID 39618643, 2024). "Although these factors above resulted in relatively low AUC values for this research, CRP and PCT remain the most referenced infection markers among physicians, given their established significance in infected diseases, especially perioperative infections." (PMID 38992621, 2024). "Thereby, the trend is that the antibodies, only partly present prior to infection, bind to those glycan fractions with lower binding to DC-SIGN, MGL, and CRP but high recognition by the anti-FLDNF, anti-LDNF, and anti-PC (TEPC-15) monoclonal antibodies." (PMID 38182041, 2024). "However, CRP levels could be elevated in other conditions associated with inflammation and may not be a reliable marker to detect the infection or denote the severity of the infection." (PMID 39493077, 2024). "Among the myriad of molecules under scrutiny, C-reactive protein (CRP) has long stood as a cornerstone in clinical practice, serving as a reliable marker of inflammation and infection." (PMID 38562275, 2024). "Another biomarker of interest is C-reactive protein (CRP), which is an acute-phase reactant synthesized by the liver in response to tissue injury, inflammation, or infection." (PMID 38668127, 2024). "Early elevated CRP was more likely correlated with positive microbiological results in urine or tracheal secretions, whereas it remains unclear at this very early time point of treatment whether this is inflammation, a relevant infection, or even microbial colonization." (PMID 39124564, 2024). "The CRP level reached its highest on day 4 in the insulin group and became gradually lower but still remained higher than that in the other groups, indicating that patients in the insulin group might develop more severe infection and inflammation than those in the other groups." (PMID 38755442, 2024). "Altogether, the value of combinatory analysis of PCT, CRP, and NEU% in the evaluation of the severity of infections is still controversial." (PMID 39305165, 2024).
infection (continued). "C-reactive protein (CRP) serial measurements in infection progression are helpful and aid infection diagnosis." (PMID 38654771, 2024). "Established markers such as C-reactive protein (CRP), procalcitonin, and interleukin-6 (IL-6) indicate infection presence and severity, aiding clinical decision-making." (PMID 38465031, 2024). "Our meta-analysis found that the effectiveness of CRP and PCT in predicting infection in necrotizing pancreatitis can vary depending on the stage of the disease." (PMID 38279274, 2024). "In the blood test, signs of infection were observed: WBC 43660/μL, ESR 120 mm/hour, CRP 38.73 mg/dL." (PMID 38172867, 2024). "Inflammatory markers such as erythrocyte sedimentation rate (ESR), C-reactive protein (CRP), and white blood cell (WBC) count clearly indicate infection, immune reaction, and inflammatory processes occurring within the body." (PMID 39310383, 2024). "infection from bacterial EOS, since CRP always appears increased upon consecutive monitoring of the latter." (PMID 39457166, 2024). "Based on the ROC curve, the accuracy of IL-6, PCT, CRP, and WBC levels on PODs 3 and 5 in predicting postoperative infection was calculated." (PMID 38504206, 2024). "The pro-inflammatory markers profile (CRP, IL1, IL6 and TNFα) was generally abnormal in the infection group in week 0 and those values seemed to improve throughout the weeks." (PMID 37762523, 2023). "On the other hand, serum levels of WBC, CRP, PCT, LDH, and ferritin showed an increasing trend with the increase in the severity of the infection." (PMID 36678211, 2023). "Infection indicators, including the white blood cell (WBC), C-reactive protein (CRP), and procalcitonin (PCT), were used to evaluate infection." (PMID 37142734, 2023). "Compared with CRP, SAA levels rise earlier and sharper, reach higher levels, and return faster to normal values when infection is cured." (PMID 37627653, 2023). "As it is well understood, CRP and LDH values tend to rise in the case of severe infection, tissue damage, or injury, as well as in chronic diseases." (PMID 38005862, 2023). "In clinical work, dynamic monitoring of leucocytes, CRP, PCT, and other laboratory indicators are often used to assess infection incidence." (PMID 36914716, 2023). "White blood cell (WBC), C‐reactive protein (CRP), procalcitonin (PCT), serum amyloid A (SAA) and erythrocyte sedimentation rate (ESR) are highly sensitive markers for infection and inflammation." (PMID 37142438, 2023). "The findings of the study shed light on several key aspects in relation to UTIs, encompassing patient demographics, infection characteristics, bacterial species, PCT and CRP levels." (PMID 37821527, 2023). "CRP is a plasma protein that is synthesized in the liver, induced by IL‐1, IL‐6, and TNF‐α, and considered a marker for inflammation, infection, and tissue injury." (PMID 36314077, 2023). "Elevated inflammatory marks, such as white blood cell count, CRP, PCT, or IL-6, also suggest the possibility of concurrent infection." (PMID 38444540, 2023). "CRP and WBC are the most common laboratory parameters used in detecting and following up infections as they are more sensitive compared to different radiological modalities." (PMID 37872533, 2023). "The C-reactive protein (CRP) is a cheap laboratory parameter that is widely used in clinical routines as the most important acute-phase serum protein to detect and monitor infection." (PMID 37107100, 2023). "IL-6, neutrophil count, % neutrophils, NLR, PLR, CRP, AST, and urea increased with the severity of the infection." (PMID 36838284, 2023). "When adding CRP to multivariable models including age, CEA, infection history, and chemotherapy, the ROC AUC showed an increase of 0.17 compared to the model without CRP." (PMID 38074681, 2023).
infection (continued). "Despite early intervention with debridement and aggressive intravenous antibiotic treatment, the five-day post-operative blood biochemistry results indicated the persistence of the infection with an ESR of 39 (mm/hr), CRP 174 (mg/L), and WBC 12 (*109/L)." (PMID 37303456, 2023). "Outliers with elevated biomarkers observed in both pre-infection specimens included IL-1β (N=1 participant), suPAR (N=2), MCP-1/CCL2, sCD163, and CRP (N=3), TNFα (N=9) and/or leptin (N=23)." (PMID 37461626, 2023). "If serum CRP level continuously increases from 4th to 7th day after surgery, a high probability of FRI should be considered after exclusion of infection in other systems or persistent systemic inflammatory stress status of the patient." (PMID 37153693, 2023). "The sensitivity of the test for predicting infection decreased slightly in cases of combined use of CRP and NLR compared to CRP above 40 mg/L but its specificity was noticeably higher than CRP above 40 mg/L." (PMID 37016028, 2023). "In contrast to CRP, WBC counts remained within a normal range, even in presence of postoperative infections, which results in a very low sensitivity of 36.4%." (PMID 36631814, 2023). "For instance, it was discussed that CRP values can fluctuate by the day, that blood samples collected in EDs may be those before elevated concentrations of CRP, and that they have been known to reach their peak between 36–50 h after the onset of infection [1243,1244,1245]." (PMID 37873776, 2023). "Early infection status was excluded in all patients; however, in the group SGF+DGF, the serum CRP level was significantly higher (17.2 (7.5–26.0) mg/L vs. 27.0 (11.9–46.56) mg/L, p = 0.013)." (PMID 38003980, 2023). "With respect to nutritional status, most studies have highlighted CRP and PCT as solid markers of concurrent infection in malnourished children, similar to the acute-phase response of well-nourished children." (PMID 37892278, 2023). "In terms of infection indicators, WBS, CRP and PCT were 8.18 ± 1.89, 4.23 ± 6.5 and 0.12 ± 0.17 after the treatment." (PMID 37142734, 2023). "Previous studies have shown that serological markers such as C-reactive protein (CRP) and erythrocyte sedimentation (ESR) are unreliable markers for evaluating the persistence of reimplantation infection." (PMID 37187468, 2023). "The areas under the curve for diagnosing infection for PCT, DNI, CRP, and SAA were 0.770, 0.817, 0.870, and 0.904, respectively." (PMID 37046430, 2023). "When compared to CRP, PCT levels increase faster after stimulation, reach their peak faster, and also decline faster after resolution of infection." (PMID 36941681, 2023). "Coupled to the pro-inflammatory cytokine response, levels of acute phase proteins such as CRP and SAA can also change during periods of trauma and infection." (PMID 37022674, 2023). "The erythrocyte sedimentation rate (ESR), C-reactive protein (CRP) and procalcitonin (PCT) are sensitive markers of infection, but they also lack specificity for the diagnosis of spinal infections." (PMID 36844401, 2023). "Following the changing pattern of post-operative CRP and WBC counts and compare them to the patient’s clinical condition to find which one is better for early detection of early infection." (PMID 37872533, 2023). "For CRP, PCT, and IL-6 provide results in an hour, but the time from initiation of infection to biomarker detection takes about 1–3 h." (PMID 37932249, 2023). "The mean values of certain blood parameters increased accordingly with the severity of the infection: leucocyte count, neutrophil count, % neutrophils, NLR, PLR, CRP, urea, and creatinine." (PMID 36838284, 2023). "Serum C-reactive protein (CRP) is a marker of inflammation and is elevated in response to tissue damage or infection." (PMID 38040848, 2023). "Levels of CRP, ESR, FIB, GLO, and CAGR were significantly higher in the infection group than in non-infection group (P < 0.05)." (PMID 38111666, 2023).
infection (continued). "There were also multiple endothelial markers that that were downregulated in severe infection including ICAM-1 (p = 0.02) and C-reactive protein (CRP) (p = 0.0003)." (PMID 37598150, 2023). "CRP POCT adds to the complete understanding of a patient’s situation and reduces subjectivity when assessing the severity of an infection and deciding on further patient treatment or management." (PMID 37324137, 2023). "Our findings corroborate that GCS, MVT, albumin, CRP, smoking, and DCI are important predictors of postoperative infection and enable physicians to make informed decisions and implement appropriate clinical interventions to reduce the risk of POP." (PMID 37745673, 2023). "C-reactive protein (CRP): Increased levels of CRP are a reliable indication of inflammation and are frequently employed as an indicator for infection problems." (PMID 38264378, 2023). "The concentration of the C-reactive protein (CRP), an acute phase protein, is rapidly rising in response to trauma, inflammation, infection, and several malignancies." (PMID 37009523, 2023). "In the recovery phase (D10), as the immune system and treatment brought the infection under control, WBC and levels of IL-6, CRP, hepcidin, and LCN2 substantially decreased compared to the acute phase of infection." (PMID 37932342, 2023). "Blood infection parameters were relatively high before surgery in both groups (ACDF: CRP, 156.5 ± 12.7 mg/L; leukocytes, 13.6 ± 5.6 × 109/L vs. corpectomy: CRP, 120.0 ± 22.3 mg/L; leukocytes, 13.1 ± 8.0 × 109/L; p > 0.05)." (PMID 36629954, 2023). "Other biomarkers used clinically to indicate infection are fever, high WBC count (>12 K), and increases in C-reactive protein." (PMID 37583625, 2023). "Risk thresholds based on Youden index to discriminate mild infection form severe infection/septic shock were 61.7 ng/ml for PSP, 125.9 mg/l for CRP and 1.1 ng/ml for PCT." (PMID 37707744, 2023). "The most commonly used clinical biomarkers for infection are procalcitonin (PCT) and C-reactive protein (CRP)." (PMID 37114211, 2023). "Blood levels of inflammatory markers such as interleukin 6 (IL-6) and C-reactive protein (CRP), as well as white blood cell (WBC) count, rose during the infection's acute period (D1 and D3)." (PMID 37932342, 2023). "C-reactive protein (CRP) is an acute phase, predominantly hepatically synthesized protein, secreted in response to cytokine signaling at sites of tissue injury or infection with the physiological function of acute pro-inflammatory response." (PMID 37781355, 2023). "Four days later, laboratory evaluation showed an elevated C-reactive protein (CRP) value of 96.9 mg/L and a decreased white blood cell (WBC) count of 2800/μL, and he had a body temperature above 38 °C, suggestive of severe infection." (PMID 36800616, 2023). "There are several classic infection-related indicators, particularly are procalcitonin (PCT) and C-reactive-protein (CRP)." (PMID 37953798, 2023). "Next, using the decision tree algorithm (QUEST method), we found cutoff points for CRP and NLR for their combined use in predicting an infection." (PMID 37016028, 2023). "This study evaluated and compared the clinical utility of PCT, DNI, CRP, and SAA levels in diagnosing infection in patients with hematologic diseases." (PMID 37046430, 2023). "(IC): The analyzed biochemical parameters of CRP, NLR, WBC, and D-Dimer in the group of patients with infection of the upper and lower part of the face were above the norm or at the upper limit of normal values (WBC)." (PMID 36981782, 2023). "C-reactive protein (CRP) is currently employed as a useful measure of inflammation and infection, being considered as a more reliable marker of infection-related surgical complications than erythrocyte sedimentation rate and white blood cell (WBC) count." (PMID 37568175, 2023). "Cutoff points of CRP and NLR in predicting an infection diagnosis were evaluated using the area under the ROC curves (AUCs) in the training group." (PMID 37016028, 2023).
infection (continued). "The main laboratory test to monitor response to antibiotic treatment is CRP, as ESR is a poorer predictor, because it tends to remain elevated for several weeks after resolution of the acute phase of the infection." (PMID 36911022, 2023). "Our findings further underscore that patients with severe infections, characterized by heightened levels of PCT and CRP, manifest escalated serum concentrations of IL-10." (PMID 37986183, 2023). "In this study, we assessed the inhibition of infection based on changes in the acute phase reaction markers, ESR and CRP, as additional criteria for PJI." (PMID 36851713, 2023). "A statistically significant difference in CRP and NLR levels was observed between infections which source was a deciduous tooth and a permanent tooth." (PMID 36981782, 2023). "CRP and WBC are specific indicators of early infection and inflammation and can also reflect the traumatic stress response of surgery." (PMID 37041392, 2023). "IL-6 induces the production of C-reactive protein (CRP) and procalcitonin (PCT), which are directly related to inflammatory diseases and the severity of infection." (PMID 37158301, 2023). "We excluded patients with concomitant clinical infections and those needing emergency hepatectomy due to ruptured HCC, utilizing only the most recent CRP levels obtained within a week before surgery to minimize possible confounding." (PMID 38053048, 2023). "Using the best discriminatory cutoff value of 5.32 for identifying infections, the sensitivity of NLR was only 54.76%, which was significantly weaker compared to the sensitivity of the CRP level at a cutoff value of 15.48 mg/L (76.19%)." (PMID 37761321, 2023). "Only 210 (43%) had signs of infection, defined as a temperature above 38 degrees celsius or biochemical markers such as raised WCC/CRP and consistent CSF abnormalities." (PMID 37365629, 2023). "Regarding infection indicators, the tDCS and conventional treatment groups showed 9.44 ± 2.07 and 10.14 ± 1.78 for WBS, 18.9 ± 20.62 and 17.73 ± 18.16 for CRP, and 0.31 ± 0.32 and 0.44 ± 0.36 for PCT." (PMID 37142734, 2023). "The significance of identifying trends in infection characteristics and levels of PCT and CRP cannot be overstated." (PMID 37821527, 2023). "If CRP is in the range of 23–82 mg/L, but with an NLR level above 9.7, there is a very high probability (over 90%) of infection." (PMID 37016028, 2023). "Regarding infection indicators, WBS, CRP and PCT were 8.18±1.89, 12.81±15.79, and 0.27±0.26 after the treatment." (PMID 37142734, 2023). "During infection episodes, hepcidin levels rise together with other markers of inflammation, such as α-1 glycoprotein (AGP) and C-reactive protein (CRP)." (PMID 36675141, 2023). "C-reactive protein (CRP) is an acute inflammatory protein and increases dramatically in response to almost tissue injury, infection and inflammation, thus being used as an inflammatory marker in clinic." (PMID 37753091, 2023). "The reduction in CRP levels and PMN count indicates a decreased infection in animals undergoing IV and IC treatment." (PMID 37438398, 2023). "qSOFA scores didn’t statistically correlate with a diagnosis of infection or AC but positively correlated with PCT and C-reactive protein (CRP) values." (PMID 37050995, 2023). "The 3 patients who suffered a recurrent infection and required a second DAIR procedure were younger (average age 66 years) and had lower CRP levels (66 mg/l versus 98 mg/l)." (PMID 37074322, 2023). "Long-established markers for infection include procalcitonin (PCT) and C-reactive protein (CRP) levels." (PMID 36399260, 2023). "The AUC of maximum CRP and PCT as predictors of infection were 0.734 and 0.762, respectively, with an overall similar quality of the model (0.64 vs. 0.67, respectively)." (PMID 37834754, 2023). "Post-operative infection indexes, namely ESR and CRP, in both groups were significantly lower than those before the operation (P < .05)." (PMID 38115351, 2023).